RPS19 (ribosomal protein S19)
Description:
Component of the small ribosomal subunit. The ribosome is a large ribonucleoprotein complex responsible for the synthesis of proteins in the cell. Required for pre-rRNA processing and maturation of 40S ribosomal subunits. Part of the small subunit (SSU) processome, first precursor of the small eukaryotic ribosomal subunit. During the assembly of the SSU processome in the nucleolus, many ribosome biogenesis factors, an RNA chaperone and ribosomal proteins associate with the nascent pre-rRNA and work in concert to generate RNA folding, modifications, rearrangements and cleavage as well as targeted degradation of pre-ribosomal RNA by the RNA exosome.
Synonyms: S19; eS19; DBA; DBA1; LOH19CR1
Tractability: Small molecule: an approved drug acts on it; a structure with a bound ligand is known; a high-quality ligand is known. PROTAC: ubiquitination databases record sites on it; its protein half-life has been measured; a small molecule that binds it is known. Other modalities: a drug acting on it is in phase 2 or 3 trials.
Target class: Other cytosolic protein
Gene: Protein-coding gene on chromosome 19 (41,860,255 to 41,872,925, forward strand). Ensembl gene ENSG00000105372.
Subcellular location: Cytoplasm; Nucleus, nucleolus
Subcellular location (Human Protein Atlas): Nucleoplasm
Pathways (Reactome):
Metabolism of proteins: Eukaryotic Translation Termination; Formation of a pool of free 40S subunits; Formation of the ternary complex, and subsequently, the 43S complex; GTP hydrolysis and joining of the 60S ribosomal subunit; L13a-mediated translational silencing of Ceruloplasmin expression; PELO:HBS1L and ABCE1 dissociate a ribosome on a non-stop mRNA; Peptide chain elongation; Ribosomal scanning and start codon recognition; SRP-dependent cotranslational protein targeting to membrane; Translation initiation complex formation; ZNF598 and the Ribosome-associated Quality Trigger (RQT) complex dissociate a ribosome stalled on a no-go mRNA
Disease: SARS-CoV-1 modulates host translation machinery; SARS-CoV-2 modulates host translation machinery; Viral mRNA Translation
Metabolism of RNA: Major pathway of rRNA processing in the nucleolus and cytosol; Nonsense Mediated Decay (NMD) enhanced by the Exon Junction Complex (EJC); Nonsense Mediated Decay (NMD) independent of the Exon Junction Complex (EJC)
Cellular responses to stimuli: Response of EIF2AK4 (GCN2) to amino acid deficiency
Developmental Biology: Regulation of expression of SLITs and ROBOs
Metabolism: Selenocysteine synthesis
Gene Ontology:
Molecular function: fibroblast growth factor binding; identical protein binding; protein binding; RNA binding; structural constituent of ribosome
Biological process: antimicrobial humoral immune response mediated by antimicrobial peptide; defense response to Gram-negative bacterium; erythrocyte differentiation; killing of cells of another organism; maturation of SSU-rRNA; maturation of SSU-rRNA from tricistronic rRNA transcript (SSU-rRNA, 5.8S rRNA, LSU-rRNA); monocyte chemotaxis; negative regulation of respiratory burst involved in inflammatory response; nucleolus organization; positive regulation of respiratory burst involved in inflammatory response; ribosomal small subunit assembly; ribosomal small subunit biogenesis; rRNA processing; cytoplasmic translation; translation
Cellular component: cytoplasm; cytosol; cytosolic ribosome; cytosolic small ribosomal subunit; extracellular exosome; focal adhesion; membrane; nucleolus; nucleoplasm; postsynaptic density; ribosome; small-subunit processome
Genetic constraint (gnomAD): Loss-of-function variants: 1 observed, 19.85 expected, observed/expected ratio (o/e) 0.0504, 90% interval 0.017 to 0.24. The upper end of that interval is the gene's LOEUF score, 0.24, which puts it in group 1 of 6, group 1 being the genes least tolerant of losing a copy. Missense variants: 111 observed, 200.87 expected, observed/expected ratio (o/e) 0.55, 90% interval 0.47 to 0.65. Synonymous variants: 87 observed, 78.91 expected, observed/expected ratio (o/e) 1.1, 90% interval 0.93 to 1.32.
Gene-disease validity (ClinGen):
ClinGen rates the evidence that RPS19 causes each of these diseases.
Diamond-Blackfan anemia (autosomal dominant): Definitive. A congenital aregenerative and often macrocytic anemia with erythroblastopenia.
Homologues: Orthologues: chimpanzee RPS19 (100% identical), pig RPS19 (100% identical), tropical clawed frog rps19 (92% identical), zebrafish rps19 (88% identical), Drosophila melanogaster RpS19b (59% identical).
Diseases named in the same sentence as RPS19 in open-access papers:
RPS19 is named in the same sentence as 88 diseases in open-access papers, as found by Europe PMC text mining. Sharing a sentence is not in itself a finding about the gene and the disease. The quoted sentences say what the papers report.
Diamond-Blackfan anemia (61 papers, 2004 to 2025). "Clinically applicable lentiviral vectors restore characteristic defects of hematopoietic stem cells from RPS19-deficient Diamond-Blackfan anemia patients." (PMID 38775150, 2024). "This study lays the groundwork for future lentivirus-mediated gene therapy in patients with Diamond Blackfan anemia (DBA) caused by mutations in ribosomal protein S19 (RPS19), showing evidence of a new safe and effective therapy." (PMID 38775150, 2024). "Specifically, mutations in RPS19 in patients with Diamond-Blackfan anemia affect proliferation and apoptosis of BM CD34+ progenitors." (PMID 36821386, 2023). "This mutation, when introduced into a mouse RPS19 model of Diamond Blackfan Anaemia, resulted in the loss of anaemia in mice." (PMID 37526268, 2023). "Morpholino targeted on Rps19 caused a deficiency of ribosomal proteins (RPs) in ZF and led to the development of Diamond Blackfan Anemia (DBA) associated with anemia, congenital defects, and cancer." (PMID 36142160, 2022). "Most patients with Diamond Blackfan anemia harbor mutations in genes coding for ribosomal subunits, the most common being RPS19, that lead to a selective impaired production of full-length GATA1 and GATA1-Short23,50,51." (PMID 31628330, 2019). "RPS19, a component of the 40S subunit, is mutated in Diamond-Blackfan anaemia, a congenital erythroid aplasia characterised by defective erythroid progenitor maturation." (PMID 29016636, 2017). "Diamond-Blackfan anemia (DBA) (MIM 105650) was the first ribosomopathy to be associated with genetic mutations in ribosomal proteins when a mutation in ribosomal protein S19 (RPS19) was first reported in 1999." (PMID 26961822, 2016). "By applying EMSA and ChIP methodologies in mouse erythroleukemia cells we show that GATA1 and PU.1 bind in vitro and in vivo the proximal promoter region of the RPS19 gene which is frequently mutated in Diamond-Blackfan Anemia." (PMID 26447946, 2015). "Mutations of the ribosomal gene RPS19 have been associated with Diamond-Blackfan anemia (DBA), which is a constitutional erythroblastopenia characterized by absent or decreased erythroid precursors, in a subset of patients." (PMID 22496757, 2012). "Nevertheless, most studies of RPS19 examined mutations in the RPS19 gene in patients with Diamond-Blackfan anemia." (PMID 22272377, 2012). "Diamond-Blackfan anemia is associated with an increased frequency of OS and mutations in ribosomal genes (i.e., RPS19, RPS24 and RPS17)." (PMID 21619704, 2011). "We focused our efforts on the resequencing analysis of the RPS19 gene locus, a region that has been linked to two forms of anemia, namely Diamond-Blackfan Anemia (DBA) and Transient Erythroblastopenia of childhood (TEC)." (PMID 19587786, 2009). "Here, we report a case of CDH in a patient with Diamond-Blackfan anemia owing to an RPS19 mutation." (PMID 31574871, 2019). "A mouse model for DBA that contains a loss-of-function point mutation in the Rps19 gene has been demonstrated to have a dominant negative effect and, importantly, mice with Rps19 deficiency develop bone marrow failure and symptoms like patients with Diamond-Blackfan anemia." (PMID 29954325, 2018). "Mutations in RPS19 are also associated with 25% of Diamond-Blackfan anemia cases (DBA)." (PMID 24658219, 2014). "Furthermore, our results indicate that rare polymorphic 5′UTR variants reduce RPS19 protein levels with implications for Diamond-Blackfan anemia." (PMID 21412415, 2011).
Diamond-Blackfan anemia (continued). "Furthermore, germline mutations in RPS19, which occur in patients with Blackfan–Diamond syndrome, a cancer susceptibility syndrome associated with haematological malignancies, have already established a role for the loss of RP in cancer." (PMID 19401700, 2009). "In humans, there is a possible association of mutations in one particular RP gene with cancer: approximately 25% of both sporadic and familial cases of Diamond-Blackfan anemia (DBA) are associated with a mutation of rpS19, and this syndrome includes an increased risk of developing leukemia." (PMID 15138505, 2004). "Diamond-Blackfan anemia (DBA) is a genetic blood disease caused by heterozygous loss-of-function mutations in ribosomal protein (RP) genes, most commonly RPS19." (PMID 36413407, 2023). "There are abundant genetic and experimental evidences demonstrate that Diamond-Blackfan anemia (DBA), a dominant autosomal bone marrow failure syndrome, is due to mutations in ribosomal genes including RPS19, RPS24, RPL5, RPL11, and RPS29, etc8-12." (PMID 31523176, 2019). "One notable syndrome is Diamond-Blackfan anemia (DBA) caused by mutations in ribosomal proteins (RPS19, RPL11, RPL5 and others) leading to defective 40S or 60S ribosomal subunit production with elevated risk of leukemia and osteosarcoma." (PMID 21152184, 2011). "For example, the Diamond-Blackfan Anemia (DBA) is caused by heterozygous loss-of-function mutations in genes encoding RPs, such as RPS19, RPL5, and RPL11, while the 5q-syndrome is caused by a somatically acquired deletion of chromosome 5q, which leads to haploinsufficiency of RPS14." (PMID 30862090, 2019). "Disrupted ribosome biogenesis by knocking down RPS19 (ribosomal protein S19) is connected to the ribosomopathy syndrome Diamond Blackfan Anemia (DBA)." (PMID 31114481, 2019). "For example, the knockdown of RPS19 or RPS24 in primary fibroblast cells from Diamond-Blackfan anemia (DBA) patients triggered cell cycle arrested at the G1 phase and G2/M phase, respectively, leading to a marked reduction in cell proliferation capacity." (PMID 29045730, 2017). "Mutations of RPS19, as well as of two other ribosomal proteins, RPS24 and RPS17, have been linked to the rare congenital disease Diamond-Blackfan Anemia." (PMID 28680364, 2016). "RPS17 along with RPS19 and RPS24 have been linked to diseases in humans including Diamond-Blackfan Anemia, an erythroid aplasia resulting in a deficiency of red blood cell precursors in the bone marrow." (PMID 25853866, 2015). "In humans, mutations in RPs have been implicated in hematopoetic disorders, most notably Diamond-Blackfan anemia (DBA), which has been attributed to mutations in RPS19, RPS26, RPS24, RPS17, RPS10, RPS7, RPL35a, RPL26, RPL11, and RPL5." (PMID 23382688, 2013). "The Ribosomal protein S19 gene locus (RPS19) has been linked to two kinds of red cell aplasia, Diamond-Blackfan Anemia (DBA) and Transient Erythroblastopenia in Childhood (TEC)." (PMID 19587786, 2009). "Patients with Diamond-Blackfan anaemia (DBA) show haploinsufficiency of the closely related ribosomal protein RPS19, and show a consequent downregulation of multiple ribosomal- and translation-related genes." (PMID 18477045, 2008). "The only reported case of an RP gene mutation in human disease is Diamond-Blackfan anemia (DBA; OMIM 105650): RPS19 is heterozygously mutated in 25% of unrelated patients with this disease." (PMID 17183665, 2006). "Mutations in RPS19, RPS28, RPS10 and RPS5 result in the ribosomopathy Diamond-Blackfan anaemia." (PMID 34283226, 2022). "The patient tested negative for pathogenic variants in genes associated with Diamond-Blackfan anemia: RPS19, RPL5, RPL11, RPS26, RPL35a, and RPL15." (PMID 35774100, 2022).
Diamond-Blackfan anemia (continued). "Further, mutations in several ribosomal protein (RP) genes, such as RPS19, RPL5, RPL11, RPL35A, RPS10, RPS17, and RPS24, cause Diamond-Blackfan anemia (DBA)." (PMID 38820160, 2024). "In the context of Diamond-Blackfan anemia (DBA), LV-based expression of the ribosomal protein S19 (RPS19) provided cure of DBA and lethal bone marrow in an RPS19-deficient DPA mouse model." (PMID 36992407, 2023). "The most well characterized is Diamond Blackfan anemia (DBA), which results from haploinsufficiencies in several different RP genes (RPS24/eS24, RPS17/eS17, RPL35A/eL33, RPL5/uL18, RPL11/uL5, RPS7/eS7, RPL36/eL36, RPS15/uS19, RPS27A/eS31) and RPS19/eS19, which is mutated in 25% of patients." (PMID 33565275, 2021). "Four RP genes, RPS19 RPS24, RPS17, and RPL35a are known to be mutated in Diamond-Blackfan anemia (DBA; MIM 105650), a congenital erthyroid aplasia characterized by macrocytic anemia." (PMID 19129914, 2009). "For example, if the recipient was being tested for Diamond-Blackfan anemia due to pure red cell aplasia, and has a heterozygous RPS19 variant, a large quantity of donor DNA that is negative for the variant (wild type) could decrease the signal for the variant nucleotide." (PMID 33316904, 2020). "Defects in several ribosomal proteins including RPS19, RPL11 and RPS14 have been observed in two types of anemia: Diamond Blackfan Anemia and 5q- syndrome." (PMID 31619461, 2019). "They include for instance TCOF1 (Treacher-Collins-Franceschetti syndrome 1) and ribosomal proteins S19 and S24 (RPS19, RPS24) in Diamond-Blackfan anemia." (PMID 23935987, 2013).
anemia (29 papers, 2004 to 2025). A reduction in the number of red blood cells, the amount of hemoglobin, and/or the volume of packed red blood cells. "We present a rare case of a 56-day-old female infant with a de novo RPS19 mutation, who presented with severe anemia and shock, and subsequently experienced growth retardation during follow-up." (PMID 40492264, 2025). "This case report describes a severe case of DBA in a 56-day-old infant with life-threatening anemia (Hb 18 g/L), metabolic acidosis (pH 6.61), and shock caused by a de novo RPS19 mutation (c.3G > T)." (PMID 40492264, 2025). "They concluded that enforced expression of RPS19 cures anemia and prevents fatal bone marrow failure in RPS19-deficient mice." (PMID 38891052, 2024). "Another study showed that the administration of L-leucine significantly improved anemia in RPS19-deficient mice, increased the bone marrow cellularity, and alleviated stress hematopoiesis." (PMID 26961822, 2016). "In RPS19-deficient DBA, the impaired 40S ribosomal subunit biogenesis suggests impaired translation as the mechanism that causes anaemia in DBA." (PMID 18477045, 2008). "First, the insufficient production of RBC due to a de novo RPS19 mutation led to severe anemia." (PMID 40492264, 2025). "Notably, RPS19 is the first and most common mutated gene, accounting for approximately 25% of cases and represents a significant cause of severe anemia in infants." (PMID 40492264, 2025). "In addition, RPS19 of network module 6, encoding a ribosomal protein, has been linked to anemia, too." (PMID 32728112, 2020). "The Rps19-deficient mice displayed macrocytic anemia, leukocytopenia, and variable platelet counts." (PMID 31600948, 2019). "It has been demonstrated that haploinsufficiency of ribosomal proteins Rps14 and Rps19 causes symptoms resembling DBA in zebrafish such as anemia and craniofacial dysplasia, and also that treatment with L-Leucine reduces the severity of both anemia and developmental deficits." (PMID 24550838, 2014). "Preclinical studies using lentiviral vectors to deliver genes like RPS19, have shown promise in restoring erythropoiesis and resolving anemia in mouse models." (PMID 40492264, 2025). "Causally, deficient RPS19, mutations of which are most frequent in DBA, directly leads to anemia in mice." (PMID 39086661, 2024). "Their study showcased that this vector effectively rescues the anemia and lethal BM failure phenotype observed in the mouse models of RPS19-deficient DBA, with low risk of mutagenesis and a highly polyclonal insertion site pattern." (PMID 38891052, 2024). "Treatment of embryos with amino acid L-Leucine, a potent activator of the mTOR pathway and mRNA translation, has been shown to alleviate anemia in rps14 and rps19 morpholino knock-down zebrafish embryos." (PMID 26624285, 2015). "Indeed, l-leucine, a drug in testing for DBA, has already proven effective in treatment of both mutant Rps14- and Rps19-driven anemia in zebrafish." (PMID 29255698, 2017).
anemia (continued). "Their results revealed that recipients transduced with EFS-RPS19 shRNA BM exhibited near normal blood cellularity, indicating that enforced expression of RPS19 driven by the EFS promoter can effectively treat severe anemia and bone marrow failure in RPS19-deficient mice." (PMID 38891052, 2024). "The anaemia in DBA and the 5q− syndrome is due to a failure of erythropoiesis and intriguingly both disorders show haploinsufficiency for ribosomal proteins, RPS19 and RPS14 respectively, required for the maturation of 40S ribosomal subunits." (PMID 18477045, 2008).